GATA1 (GATA binding protein 1)
Diseases named in the same sentence as GATA1 in open-access papers (continued):
Sharing a sentence is not in itself a finding about the gene and the disease.
cancer (52 papers, 2008 to 2025). A tumor composed of atypical neoplastic, often pleomorphic cells that invade other tissues. "Research findings reveal that the GATA1 is also associated with poor progression and prognosis of cancer." (PMID 36210802, 2022). "Its C allele has been associated with cancer, suggesting that it interferes with the binding of the GATA-1 and GATA-2 transcription factors to the estrogen receptor." (PMID 23574728, 2013). "GATA1 also enhances the gemcitabine resistance in PANC-1 cancer cells by activating antiapoptotic signalling, thereby reducing chemotherapy-induced cell death." (PMID 41294859, 2025). "Recent evidence has also suggested that GATA1 and heme work together to sustain high mitochondrial bioenergetics, essential for the rapid growth and spread of cancer cells." (PMID 40259045, 2025). "Ultimately, hsa-miR-876-3p, present at high levels only in the CAF-P-derived EV, downregulated GATA1 in cancer cells." (PMID 38169528, 2024). "As important transcriptional regulators, OCT-1 and GATA-1 are involved in the regulation of a variety of physiological and pathological processes, including the development of cancers." (PMID 31783675, 2019). "The six GATA family members from GATA1 to GATA6 were explored in human cancers by the Oncomine online database." (PMID 30872657, 2019). "Some are frequently involved in cancer cell proliferation, including two nuclear factor NF-κB, activator proteins (AP-1 and AP-2), globin transcription factor 1 (GATA-1), interleukin six responsive element (IL6RE), and steroid-response elements." (PMID 30042674, 2018). "High expression of GATA1 is also detected in a subset of AML patients compared to other cancer types, according to TCGA." (PMID 29884215, 2018). "Suppression of FLI-1 inhibits cell proliferation and induces cell apoptosis of human cancer cell by targeting Rb, GATA-1, and BCL-2." (PMID 27304058, 2016). "Among the genes from this last category, two have been identified as “cancer genes” in the COSMIC database (GATA1 and GATA2)." (PMID 27506777, 2016). "Our data provide novel insights into VEGF transcriptional regulation and suggest GATA1/SET7 as cancer therapeutic targets." (PMID 26848522, 2016). "GATA1 is one of the members of GATA TFs family and has been linked to cancer development associated to chromosome 21 trisomy." (PMID 26151558, 2015). "However, the data in TCGA suggested that the GATA1 expression was positively correlated with the MGP expression in cancer tissues." (PMID 39684309, 2024). "It has been shown that cancer-associated fibroblast-derived extracellular vesicle (EV) treats OSCC cells to acquire cisplatin resistance, by upregulating the expression of GATA-binding protein 1 (GATA1), a downstream factor of miR-876-3p." (PMID 38711989, 2024). "DBA variants in patients with cancer/MDS refer mainly to RPS19, RPL35A, RPL11, RPL5, RPS17, and GATA1 genes (18%, 13%, 10%, 5%, 3%, and 3%, respectively; 49% unknown)." (PMID 38002903, 2023). "In addition to conferring gemcitabine resistance, GATA1 was also showed to promote cancer cell proliferation in vitro and in vivo." (PMID 31093285, 2019). "Interestingly, all GATA family members besides GATA3 were mostly downregulated in most kinds of cancers, with upregulated vs downregulated study numbers (GATA1 1:7; GATA2 6:39; GATA3 31:36; GATA4 5:18; GATA5 1:17; GATA6 16:37)." (PMID 30872657, 2019). "(A) mRNA levels of GATA1 determined by microarray in CCLE lines grouped by cancer type." (PMID 29884215, 2018). "(B) GATA1 mRNA levels determined by RNAseq in cancer patients according to TCGA." (PMID 29884215, 2018).
cancer (continued). "To further substantiate our findings and expand the context of KDM4C/GATA1's regulatory role in HNSCC, we analyzed the relationship between heme metabolism and other cancer-related pathways using the TCGA HNSCC dataset." (PMID 40259045, 2025). "Our present results revealed that CAFs strongly promote cancer progression and selectively suppress IGFBP3 expression via GATA1 transcriptional downregulation, which results in cisplatin resistance in OSCC." (PMID 38169528, 2024). "We also provide evidence for a possible role of YY1, GATA1, and C/EBPα in MGP transcription regulation in human cancers." (PMID 39684309, 2024). "The data in TCGA-THCA suggested that the GATA1 expression was inversely correlated with the NRBP2 expression in normal tissues, cancer tissues, and THCA tissues." (PMID 35491849, 2022). "Meanwhile, high positive rate of CSN5, GATA1 and ZEB1 in cancer tissues detected by immunohistochemistry and we showed that expression of SENP1 is positively correlated with expression of CSN5, GATA1, ZEB1 in our TNBC samples." (PMID 35342335, 2022). "The mRNA expression level of GATA1 and GATA2 in OC listed the moderate highest among all cancer types using the CCLE analysis." (PMID 35488350, 2022). "The ICC assay results indicated that the expression of erythroid differentiation-related proteins, including HIF-1α, EPO, c-Myc, GATA-1, and GATA-2, was increased in cancer cells treated with ATO." (PMID 34676163, 2021). "Our data show that inhibition of CREBBP/EP300 bromodomains can interfere with transcriptional outputs driven by oncogenes, such as GATA1 and MYC that function as transcription factors in cancer cells." (PMID 29884215, 2018). "SLC14A1 and TEK, underexpressed in the stage IV cancer (log2(FC) = -1.06, FDR = 0.0007; log2(FC) = -1.09, FDR = 9.26e-06), were two genes only regulated by GATA1." (PMID 25648588, 2014). "Kit is involved in many cancers and is regulated by the SCL complex (Gata1/2, SCL, Lmo2) in haematopoietic cells." (PMID 20102610, 2010). "GATA1, the first recognized member of the GATA family, functions as both tumor suppressor and promotor and has been largely reported to have important roles in the development, progression and prognosis of cancers 33-36." (PMID 34093794, 2021). "Moreover, VEGFR2 knockdown abrogated the ability of GATA1 and SET7 to promote VEGF-mediated cancer cell growth." (PMID 26848522, 2016). "Additionally, Hu et al18 found that CPEB4 was strongly induced by the important erythroid-related transcription factors Gata1 and Tal1 and that 1 CPEB4 target gene is CDK6, an important protein in cell cycle regulation and cancer development." (PMID 26166131, 2015).
hematological disorders (19 papers, 2011 to 2026). "NGS-based PGT-HLA is a valuable procedure for the treatment of GATA1-related cytopenia caused by GATA1 variants, or other haematological disorders, oncological and immunological diseases." (PMID 38961467, 2024). "These blood disorders are caused by inherited mutation and somatic mutation that alter the ability of GATA1 to bind to the DNA sequence and produce the short form of the GATA1 protein." (PMID 38784708, 2024). "Among the altered genes, a likely germline variant in GATA1 (c.-19-679_221-48delinsTC) was retained as a strong candidate that conferred germline risk for hematological malignances or solid tumors." (PMID 36765901, 2023). "FOS and JUN are transcription factors in the AP-1 family, regulating the oncogenesis of multiple types of lymphomas, and GATA1 is essential for hematopoiesis, the dysregulation implicated in multiple hematologic disorders, and malignancies." (PMID 36810839, 2023). "FOG1 and GATA1 interact both functionally and physically, and disruption of the normal interaction of FOG1 and GATA1 has been linked to a range of inherited blood disorders." (PMID 25162672, 2014). "Aside from showing how a prototypical transcription factor functions in regulating lineage fate in LT-HSCs, this result is of great importance in modeling the normal functions of the GATA1 transcription factor and the hematological diseases where it is mutated." (PMID 31628330, 2019). "Our finding is beneficial for the exploration of mutated GATA-1 in non-hematopoietic disease." (PMID 28566697, 2017). "Therefore, imbalanced gene regulation caused by qualitative and quantitative changes in GATA1 is thought to be involved in specific hematological disease pathogenesis." (PMID 28119852, 2016). "Three of them harbor clinically relevant variants in genes with a probable role in the development of inherited forms of hematological malignancies (GATA1, MSH4 and PRF1)." (PMID 36765901, 2023). "However, the upstream transcriptional regulation of GATA1—especially in humans and in hematological disorders—remains incompletely understood." (PMID 41521666, 2026). "A pool of total RNAs, obtained from peripheral blood samples of two T21 at term newborns with neither haematological disorders nor GATA-1 mutations was used as negative control (T21 negative control)." (PMID 38350611, 2024). "The abnormal expression of Gata1 is closely related to a variety of hematopoietic diseases." (PMID 36361683, 2022). "These genes were regulated by RXRα and GATA1, which are involved in hematological malignancies." (PMID 34832908, 2021). "Because the coexistence of a driver clone and the acquisition of additional mutations have been identified repeatedly in hematologic malignancies, further studies are required to elucidate how SH2B3—GATA1 and NOTCH1—STAG2 mutations contribute to the pathogenesis of hypereosinophilia." (PMID 29088303, 2017). "Three types of GATA1-related hematological malignancies have been reported." (PMID 28119852, 2016). "Consequently, imbalanced GATA1 regulation is involved in certain hematological diseases." (PMID 34832908, 2021). "Apart from their functions in MK differentiation, RUNX1, GATA1 and c-MPL as well as other epigenetic factors such as BRD4 found in this study are dysregulated in a broad spectrum of hematological malignancies as well as solid tumors." (PMID 26575292, 2015).
infection (14 papers, 2009 to 2025). The state of being infected such as from the introduction of a foreign agent such as serum, vaccine, antigenic substance or organism. "Consistent with that observation, we found that in Δdbl-GATA1 mice, infection with L. amazonensis was associated with a worse outcome, higher parasite burden, and dissemination of amastigotes." (PMID 38198296, 2024). "We individually altered the expression levels of IRF1, GATA1, and Bcl11b 24 h post-infection with ALV-J." (PMID 40075948, 2025). "By 12 wpi, Δdbl-GATA1 is severely affected by the infection with several nodular and ulcerated lesions in the skin replete with parasites as revealed by the luciferase signal, while BALB/c only begun to show signal in the lymph nodes draining the footpad." (PMID 38198296, 2024). "After 17 wpi, 80% of the Δdbl-GATA1 mice died due to infection, against 20% of deaths in infected BALB/c." (PMID 38198296, 2024). "In particular, the expression of BST-2 and GATA-1 and their networks strongly suggest that women have stronger cell-dependent and humoral responses to infection, resulting in a more rapid pathogen elimination in females than in males." (PMID 34753980, 2021). "Therefore, we aimed to describe some aspects of the infection of Δdbl-GATA1 mice with L. amazonensis." (PMID 38198296, 2024). "Thirteen weeks after infection, metastatic lesions were found in all Δdbl-GATA1 mice." (PMID 38198296, 2024). "However, nine weeks after infection, massive growth of metastatic lesions appeared in several parts of the skin in Δdbl-GATA1 mice, weeks earlier than BALB/c." (PMID 38198296, 2024). "We also noticed high levels of antibodies after infection in GATA1-/- mice, which may have contributed to the reduced parasite burden in these animals." (PMID 34784389, 2021). "Upon infection with ALV-J, there was a notable upregulation in the expressions of GATA1 and IRF1 within 24 h, followed by a subsequent decrease at 36 h post-infection (hpi)." (PMID 40075948, 2025). "Genes regulated by GATA1 and GATA2 were downregulated during acute infection, but upregulated whenever appropriate erythropoietic output was restored." (PMID 28938907, 2017). "The target genes of GATA1 and GATA2 correlated with the small but significant decrease (p = 0.045) in the frequency of the erythroid progenitor population in the BM during acute infection." (PMID 28938907, 2017). "First, the expression of GATA1 and GATA2 was examined directly to understand if the gene expression of these proteins was changed during infection, which could directly impact the erythropoietic response during infection." (PMID 28938907, 2017). "Furthermore, PBS treated control Δdbl-GATA-1 mice had higher parasite burdens than their WT BALB/c counterparts, suggesting eosinophils have a role in the control of primary infection in this more resistant genotype." (PMID 25816012, 2015). "Furthermore, stable infection with GATA1 wt, but not GATA1 S161A S187A mutant resulted in decreased E-cadherin expression and increased fibronectin, vimentin expression in MCF-7 cells or NMuMG cells." (PMID 25726523, 2015). "In the bone marrow, the mRNA expression of erythroid differentiation genes (α-globin, β-globin, ALAS2) were inhibited by 50%, but mRNA levels of erythroid receptor (c-kit, EpoR) and transcription factors (GATA1, GATA2, FOG1) were not affected by the infection." (PMID 23533629, 2013). "Metastatic lesions were not an exclusive feature of Δdbl-GATA1 mice since similar nodules were also observed in BALB/c mice, but in this case, lesions began to appear late in physiopathology progress, as the first mice died on week sixteen post-infection." (PMID 38198296, 2024).
infection (continued). "Next, the genes regulated by GATA1 and GATA2 were examined to identify whether the genes regulated by these proteins were differentially regulated even though transcription of GATA1/GATA2 was not altered significantly during acute infection." (PMID 28938907, 2017).
gastrointestinal disease (2 papers, 2022 to 2025). A disease that occurs in the gastrointestinal system, excluding the hepatobiliary system. "Vitamin D intervention suppressed the GATA1/STING signaling pathway and both type I interferon response and inflammatory reaction, thereby preventing abnormal immune reactions that lead to dysbiosis of the gut microbiota and gastrointestinal diseases." (PMID 40563965, 2025).
hematologic cancers (2 papers, 2018 to 2021). "Further studies will be needed to evaluate the relevance of GATA1 overexpression in hematologic cancers." (PMID 29884215, 2018). "GATA1-related hematological cancers have been previously reported." (PMID 34832908, 2021).
inflammation (2 papers, 2021). Aberrant reaction of the microcirculation characterized by movement of fluid and leukocytes from the blood into extravascular tissues. "Our findings of reduced IFN‐γ expression in BALB/c mice and not in Δdbl GATA‐1 mice are of particular interest, since it was discovered that eosinophil‐derived IFN‐γ induces airway hyperresponsiveness and lung inflammation even in the absence of lymphocytes." (PMID 33450054, 2021).
bacterial infections (1 paper, 2025). "Regardless of the response pattern, the combination of the responses of SQSTM1, RNASE2, and GATA1 to BYBG supplementation may improve the innate immune capacity to respond to future bacterial infections, which is a hallmark of innate immune training." (PMID 39846553, 2025).
cardiovascular diseases (1 paper, 2022). "All the GATA family members identified for mesoderm development (GATA1, 2, 4, and 6) are implicated in Human cardiovascular diseases." (PMID 36040971, 2022).
GATA1 also shares sentences with these, for which no sentence is quoted: Congenital erythropoietic porphyria (3 papers); genetic disorders (3); acute erythroblastic leukemia (2); congenital dyserythropoietic anemia (2); diabetes (2); lymph node metastasis (2); sarcoma (2); squamous cell carcinoma of the lung (2); Zinc deficiency (2); acquired aplastic anemia (1); acute kidney injury (1); acute promyelocytic leukemia (1); adenocarcinoma (1); adenomyosis (1); atopic dermatitis (1); beta thalassemia (1); beta-thalassemia major (1); Bloom syndrome (1); cholangiocarcinoma (1); cleft palate (1); congenital anemia (1); congenital heart defects (1); congenital neutropenia (1); diffuse large B-cell lymphoma (1); dilated cardiomyopathy (1); Down syndrome acute megakaryoblastic leukemia (1); dyskeratosis congenita (1); eosinophilic diseases (1); eosinophilic esophagitis (1); erythroblastopenia (1).
A further 40 diseases each share a sentence with GATA1 in 1 paper.